GLTP (glycolipid transfer protein)
Description:
Accelerates the intermembrane transfer of various glycolipids. Catalyzes the transfer of various glycosphingolipids between membranes but does not catalyze the transfer of phospholipids. May be involved in the intracellular translocation of glucosylceramides.
Tractability: Small molecule: a structure with a bound ligand is known; it has a high-quality binding pocket. PROTAC: ubiquitination databases record sites on it; its protein half-life has been measured.
Gene: Protein-coding gene on chromosome 12 (109,850,943 to 109,880,541, reverse strand). Ensembl gene ENSG00000139433.
Subcellular location: Cytoplasm
Subcellular location (Human Protein Atlas): Cytosol
Pathways (Reactome):
Transport of small molecules: Glycosphingolipid transport
Gene Ontology:
Molecular function: glycolipid binding; glycolipid transfer activity; identical protein binding; lipid binding; lipid sensor activity; lipid transfer activity; protein binding; ceramide 1-phosphate binding
Biological process: endoplasmic reticulum to Golgi vesicle-mediated transport; intermembrane lipid transfer; regulation of glucosylceramide biosynthetic process; ceramide transport; glycolipid transport; response to immobilization stress
Cellular component: cytosol; cytoplasm
Genetic constraint (gnomAD): Loss-of-function variants: 13 observed, 12.97 expected, observed/expected ratio (o/e) 1, 90% interval 0.65 to 1.58. The upper end of that interval is the gene's LOEUF score, 1.58, which puts it in group 6 of 6, group 1 being the genes least tolerant of losing a copy. Missense variants: 126 observed, 148.19 expected, observed/expected ratio (o/e) 0.85, 90% interval 0.74 to 0.99. Synonymous variants: 54 observed, 59.21 expected, observed/expected ratio (o/e) 0.91, 90% interval 0.73 to 1.14.
Homologues: Orthologues: macaque GLTP (100% identical), dog GLTP (99% identical), pig GLTP (99% identical), guinea pig GLTP (97% identical), rat Gltp (94% identical), mouse Gltp (93% identical), chimpanzee GLTP (90% identical), zebrafish gltpa (80% identical), tropical clawed frog gltp (74% identical), zebrafish gltpb (72% identical), Caenorhabditis elegans Y82E9BR.14 (24% identical), Drosophila melanogaster CG6299 (23% identical), and 2 more. Paralogues in human: PLEKHA8 (37% identical), GLTPD2 (18% identical), CERT1 (17% identical), CPTP (16% identical), PLEKHA3 (7% identical).
Diseases named in the same sentence as GLTP in open-access papers:
GLTP is named in the same sentence as 21 diseases in open-access papers, as found by Europe PMC text mining. Sharing a sentence is not in itself a finding about the gene and the disease. The quoted sentences say what the papers report.
lung carcinoma (3 papers, 2022 to 2024). "TCGA database analysis showed that the lung cancer patients with lower expression levels of GLTP had a shorter time of survival than those with higher levels of GLTP." (PMID 35163707, 2022). "GLTP overexpression alone was sufficient to increase the sensitivity of lung cancer cells to gefitinib treatment." (PMID 35163707, 2022). "Our results showed that miR-196a overexpression decreased the cell sensitivity to gefitinib treatment in lung cancer and this effect was partly reversed by the upregulation of GLTP." (PMID 35163707, 2022). "Our findings provided the first evidence that the NRF2/miR-196a/GLTP pathway was an important mechanism of gefitinib resistance, and miR-196a and GLTP may be used as new biomarkers for gefitinib resistance and clinical therapeutic outcomes of lung cancer." (PMID 35163707, 2022).
autonomic dysfunction (1 paper, 2025). "The failure of gLTP expression in HSD-fed rats aligns with previous findings showing reduced gLTP expression in models of autonomic dysfunction." (PMID 41187128, 2025).
cervical cancer (1 paper, 2022). A primary or metastatic malignant neoplasm involving the cervix. "Further evidence of increased GLTP protein expression in cervical cancer tissues came from the Human Protein Atlas (HPA) immunohistochemical data as well." (PMID 35845139, 2022).
cholera (1 paper, 2021). "Both XLA and XLB specifically cross-linked GLTP, a GlcCer-binding protein, but not other GSL-binding proteins (cholera and Shiga toxins)." (PMID 34597626, 2021).
Colon cancer (1 paper, 2022). "Colon cancer cells overexpressing GLTP (HT-29) exhibit RIPK-3-mediated MLKL phosphorylation, increased intracellular Ca2+, levels and induce cell death through necroptosis." (PMID 36685937, 2022).
dysautonomia (1 paper, 2025). An acute or chronic disorder, affecting the sympathetic or parasympathetic nervous system. "We propose that the observed increase in GABA, together with the absence of gLTP, reflects the presence of BED-associated dysautonomia, characterized by reduced sympathetic activity." (PMID 41154812, 2025).
glioma (1 paper, 2008). A benign or malignant brain and spinal cord tumor that arises from glial cells (astrocytes, oligodendrocytes, ependymal cells). "To identify the human gene(s) encoding GLTP, the sequences of cDNAs that we previously cloned from GLTP mRNA of human skin fibroblasts and glioma cells (GenBank AF209074, AY372530, AY372531, AY372532) were used in BLAST searches of the NCBI Human Genome." (PMID 18261224, 2008).
Hypertension (1 paper, 2019). The presence of chronic increased pressure in the systemic arterial system. "The data presented here demonstrated that gLTP can be evoked in SHR at a young age (6 wo) before the onset of hypertension, and the known lack expression of gLTP in adult (12 wo) SHR can be reverted by antagonizing endogenous ganglionic GABA inhibition." (PMID 31737063, 2019).
keloid (1 paper, 2023). An irregularly shaped, elevated mark on the skin caused by deposits of excessive amounts of collagen during wound healing. "We explored the potential role of GSL metabolism pathway in keloid, classfied keloids based on GSLMRGs expression patterns, provided a set of gene markers including GLTP, GALC, ARSA, HEXB, SUMF2, and GBA2, and constructed a diagnostic model for keloid." (PMID 37168863, 2023). "A strong correlation between IL-7 and GLTP, GALC, ARSA, HEXB, and SUMF2 was found, suggesting that IL-7-based inflammatory factors may involve in keloid growth and development through associating with the GSL metabolism pathway." (PMID 37168863, 2023). "In this study, the differential GSLMRGs of keloid and the top ten genes with the highest importance from machine learning algorithms Random Forest and SVM-RFE were intersected, and six candidate GSLMRGs were identified: ARSA, GBA2, SUMF2, GLTP, GALC, and HEXB." (PMID 37168863, 2023).
metabolic syndrome (1 paper, 2019). A cluster of metabolic risk factors for CARDIOVASCULAR DISEASES and TYPE 2 DIABETES MELLITUS. "Interestingly, we identified a gene, GLTP, that is involved in glycolipid transfer and that has been associated with metabolic syndrome." (PMID 31481602, 2019).
prostate carcinoma (1 paper, 2014). A carcinoma that arises from epithelial cells of the prostate gland. "The other SNP, rs4766642, reportedly regulates the expression of GLTP through eQTL in prostate cancer cells, which could have an important contribution to the regulation of endothelial cell mobility." (PMID 25026280, 2014).
psoriasis (1 paper, 2015). An autoimmune condition characterized by red, well-delineated plaques with silvery scales that are usually on the extensor surfaces and scalp. "All other DEGPs could be placed along a continuum, with some showing greater psoriasis specificity (e.g., DBI, GLTP, HRNR, KRT73, ELOVL7), and others showing similar expression shifts in many or most skin diseases (e.g., MX1, S100A8, S100A9, STAT1, LAP3)." (PMID 26251673, 2015). "However, given distinct functional properties of psoriasis-specific and non-specific DEGPs, it may be appropriate for such applications to assign greater emphasis to the most psoriasis-specific DEGPs, such as NCCRP1, DBI and GLTP." (PMID 26251673, 2015).
rectal cancer (1 paper, 2025). A primary or metastatic malignant neoplasm that affects the rectum. "This study identified a TRP channel-related gene signature (BMP5, DHRS11, GLTP, NFE2L3, and TMCC3) that predicts rectal cancer prognosis and modulates tumor–immune crosstalk." (PMID 40963625, 2025). "Through qRT-PCR experiments, we found that DHRS11, GLTP, and NFE2L3 have dysregulated expression in rectal cancer tissues." (PMID 40963625, 2025).
tumor (6 papers, 2020 to 2025). "TIMER results predicted that GLTP expression in 10 types of tumor specimens (including CC specimens) was considerably greater than that in nontumor specimens." (PMID 35845139, 2022). "From the GEO database, we also found that the expression levels of GLTP were extremely low in the gefitinib resistance cells, and the expression levels of GLTP were decreased with the increase in tumor grade." (PMID 35163707, 2022). "In this study, our group aimed to explore the roles of GLTP in CC, including its expressions and prognostic values, tumor-related effects, and connection with the immune microenvironment." (PMID 35845139, 2022). "Our study established a novel six‐gene (APOC1, GLTP, ISG20, SPP1, SLC24A3 and UPP1) signature that was closely associated with the immune response and tumour immune microenvironment." (PMID 34498424, 2021). "Our study established a novel six‐gene (APOC1, GLTP, ISG20, SPP1, SLC24A3 and UPP1) signature that was closely associated with the immune response and the tumour immune microenvironment." (PMID 34498424, 2021). "GLTP downregulation in CRC aligns with its tumor-suppressive function as a MIR196B target, indicating that lipid metabolism perturbations mediated by GLTP loss may drive RC progression." (PMID 40963625, 2025). "Furthermore, as HRAS is a common mutation site in RC, the observed negative correlation between HRAS and GLTP may be associated with the tumor suppressor mechanism of GLTP." (PMID 40963625, 2025). "Notably, we established a novel six‐gene (APOC1, GLTP, ISG20, SPP1, SLC24A3 and UPP1) prognostic signature and discovered for the first time that this signature was associated not only with intrinsic aggressive features but also with the tumour immune microenvironment." (PMID 34498424, 2021). "As can be seen, the genes GLTP and PTPRN present an underexpression in tumour tissue, so attacking it through inhibitor drugs will not produce a positive consequence when slowing tumour development." (PMID 32640984, 2020).
infection (2 papers, 2016 to 2023). The state of being infected such as from the introduction of a foreign agent such as serum, vaccine, antigenic substance or organism. "In the bladder, on the fifth day post infection, mice infected with the gltP and gltI mutants had no bacteria left, whereas mice infected with the UTI89 strain had 104 CFU remaining." (PMID 37317147, 2023).
cancer (1 paper, 2022). A tumor composed of atypical neoplastic, often pleomorphic cells that invade other tissues. "Recently, studies indicated that GLTP was involved in the process of the autophagy, inflammation and cell death of cancer cells." (PMID 35163707, 2022).
GLTP also shares sentences with these, for which no sentence is quoted: anxiety disorder (1 paper); autism (1); colorectal cancer (1); lung adenocarcinoma (1); urinary tract infection (1).